CD38 (CD38 molecule)
Diseases named in the same sentence as CD38 in open-access papers (continued):
Sharing a sentence is not in itself a finding about the gene and the disease.
tumor (continued). "Besides their immunomodulatory activity, the benefit conferred by HDAC inhibitors may be contingent upon their ability to enhance the expression of antigens of tumor cells targeted by therapeutic monoclonal antibodies, including the anti-CD38 antibody daratumumab." (PMID 30956773, 2019). "Based on these results, we defined a tumor-induced plasmablast-like-enriched B cell population (TIPB) signature with the genes CD27, CD38, and PAX5." (PMID 31519915, 2019). "However, the amount of active caspase-3 (an indicator of apoptotic cell death) in immunoblots and immunostained tumor sections of tumors grown in Cd38‒/‒ mice was significantly higher than in WT mice, suggesting that loss of CD38 in the TME promoted cell death, which in turn reduced tumor size." (PMID 30159123, 2018). "Daratumumab is a human anti-CD38 mAb, which is able to trigger ADCC and CDC in vitro against CD38+ tumor cells, using either autologous or allogeneic effector cells." (PMID 30546360, 2018). "Consistently, the tumor-infiltrating TIM-1+B cells showed increases in the expression levels of CD5, CD27 and CD38 compared to the TIM-1−B cells." (PMID 30526680, 2018). "In addition, macrophages, neutrophils, eosinophils, and γδ T-cells have also been shown to induce ADCC against tumor cells coated with a therapeutic antibody, but their role in CD38 antibody-induced ADCC is currently unknown and requires further investigations." (PMID 30294326, 2018). "Numerous studies have explored the role of CD38, CD39, CD203a/PC-1, and CD73 in generating extracellular adenosine (ADO) and thus in shaping the tumor niche in favor of proliferation." (PMID 29731713, 2018). "It includes antibodies directed against tumor cells belonging to the hematopoietic lineage, lymphocytes (CD20, CD52, CD38, etc.), and myeloid cells (CD30, CD33, etc.)." (PMID 28855903, 2017). "Seven days after injection of tumor cells, Alexa680-MU1067 (50 μg/mouse, 2.5 mg/kg) specifically detected CD38+ tumors in vivo already within 1 hour after nanobody injection." (PMID 29084989, 2017). "Evidence for a tumour-initiating cell or ‘cancer stem cell’ (CSC) was first provided by Bonnet and Dick in acute myeloid leukemia where it was shown that the CD34 + /CD38- subset of cells exhibits high tumour-initiating efficiency in mice." (PMID 28904399, 2017). "The administration of EDC-CD38 yielded tumor growth inhibition of 93% as compared to 54% provided by CHOP, indicating that EDC-CD38 was active in vivo and the CD38-NKA interaction was preserved." (PMID 27434591, 2016). "Immunohistochemically, the tumor cells were strongly positive for CD79a, CD138, CD38 and MUM-1, as well as the presence of kappa light chain restriction." (PMID 26376733, 2015). "In EMP portion, the tumor was composed of monomorphic plasmacytoid-appearing cells with immuno-positive to CD79a, CD138, CD38, MUM-1 and CD56, but lack immunoreactivity to pan-CK (AE1/AE3), CD20, CD21 and EBERs." (PMID 26376733, 2015). "As anticipated, we observed high expression of CD38 (>90%) and CD184 (>70%) in tumor cells from both patients however, CD28 expression was observed in <10% of gated tumor cells from either patient." (PMID 25853860, 2015). "All cases were immunoreactive for CD38, CD138 and MUM1 confirming plasma cell differentiation of the tumor cells." (PMID 26108914, 2015). "TRPM2 serves to couple CD38/ADPR activation with sustained Ca2+ signals and contributes to potentiating NK cell cytotoxicity against tumor cells in the mouse model." (PMID 25879940, 2015). "The phenotype of tumor initiating cells, CD34+/CD38− cells, in leukemia is similar to normal hematopoietic progenitor cells." (PMID 23443123, 2012). "Although most of the recently activated Tregs were capable of migrating to the tumor microenvironment (as determined by CCR4+ expression), CD38+ effector T cells were mostly CCR4−." (PMID 24213326, 2012).
tumor (continued). "This combinatorial strategy also reshaped the tumor immune landscape by increasing activated NK cells, elevating Granzyme B expression in CD4+ T cells, and decreasing immunosuppressive M-MDSCs expressing CD39, CD38, and CD73." (PMID 41668741, 2026). "Our observations reveal that the CD38-NAD+ axis dictates the lactate flux in Tregs by redirecting its utilization toward the generation of PEP rather than fueling the TCA cycle, thereby supporting Tregs function at the tumor site." (PMID 40117361, 2025). "Despite advancements in therapies targeting established antigens, such as BCMA, CD38, SLAMF7, and GPRC5D, specific challenges persist, including antigen escape, treatment resistance, and off-tumor toxicity, highlighting the urgent need for novel therapeutic modalities." (PMID 40597436, 2025). "Moreover, CD38 knockdown has shown to enhance the functionality of CD19 CAR-T cells and improves tumor responsiveness." (PMID 39856752, 2025). "Compared to standard EVs, CD38‐EVs exhibited enhanced uptake by CD38high tumour cells and reduced uptake by CD38‐negative non‐tumour cells in vitro." (PMID 40317915, 2025). "All three CD38-specific BARs induced dose-dependent and time-dependent CDC against tumor cells." (PMID 41254160, 2025). "In various in vivo models leveraging syngeneic mice bearing tumors with or without CD38 expression, administration of CD38-murine AttenukineTM mediated anti-tumor efficacy with increased immune activation and intra-tumoral infiltration." (PMID 40315226, 2025). "Our data indicate robust anti-tumor activity of CD38-directed AttenukineTM across multiple in vivo mouse models, several of which do not express CD38 on the tumor cells." (PMID 40315226, 2025). "Anti-tumor activity of hCD38-hAtt in these xenograft tumor models did not directly correlate with the levels of expression of CD38 or IFNAR2 of these tumor cell lines in vitro." (PMID 40315226, 2025). "Tumour volume increased rapidly in the PBS, EVs‐Doxi.v and CD38‐EVs‐Doxi.v groups." (PMID 40317915, 2025). "In the subset of patients with an increase in the percentage of CD38+ lymphocytes in response to modakafusp alfa, there were also increases in CD8+ and CD4+ T-cell activation (%CD69) as well as CD8+ T-cell cytotoxic function (%GzB) in the tumor biopsies." (PMID 41445795, 2025). "In summary, our data indicate that a CD38-directed AttenukineTM can deliver the desired tumor-directed and immune-directed impacts of IFNαtherapy without inducing tolerability issues." (PMID 40315226, 2025). "We evaluated the role of CD38 as a determinant of tumor immune microenvironment in SCLC with bulk and single-cell transcriptomic analyses and protein assessments of clinical samples and preclinical models, including CD38 in vivo blockade." (PMID 38533509, 2024). "Our findings in this study revealed that the levels of circulating CD8+CD38+ T cells, CD8+CD28+ T cells, and NK cells are potential prognostic factors for tumor response and long-term survival in patients with HCC treated with TACE, administered with or without PD-1 inhibitors." (PMID 38404585, 2024). "Nevertheless, further research is essential to define whether CD38 has any context-specific role in influencing the differentiation of exhausted CD8+ T cell subsets, particularly in chronic LCMV infection vs. tumor-bearing hosts." (PMID 38451948, 2024). "We assessed the pharmacokinetics, biodistribution, and CD38 specificity of [68Ga]Ga‐AJ206 in vitro and in vivo using multiple MM cell lines with variable CD38 levels, primary MM cells and their xenografts, and in disseminated tumor models." (PMID 38421139, 2024). "It has previously been reported that CD38-mediated immunosuppression is a mechanism of tumor cell escape from PD-1/PD-L1 blockade in non-small cell lung cancer (NSCLC) and co-inhibition of CD38 and PD-L1 improved antitumor immune response in preclinical models of NSCLC." (PMID 38533509, 2024).
tumor (continued). "In GCV control mice, PD-L1 inhibition had no impact on mRNA levels of Cd206, Cd38, Cd80 and Il-1β, highlighting the relevance of tumour biology and systemic impact of cancer on the side effects of PD-L1 inhibitors." (PMID 39834851, 2024). "Another correlative study of RRMM patients from the CoMMpass trial showed higher CD47 expression along with low CD38 expression correlated with worse overall survival and that dual inhibition of CD38 and CD47 had anti-tumor efficacy over single target inhibition." (PMID 38322418, 2024). "Notably, the on-target off-tumor T cell activation and cytokine secretion were higher for CD3 × CD38 × BCMA compared to ISB 2001." (PMID 39261676, 2024). "Antibody with the anti-CD47 Fab in the absence of the anti-CD38 Fab failed to elicit CDC of tumor cells." (PMID 38448430, 2024). "The ecto-enzymatic activity of CD38 leads to the synthesis of cADPR from NAD+ and also the production of extracellular adenosine, which may contribute to immune evasion of tumor cells." (PMID 38765013, 2024). "Studies have found that resistance is associated with genetic mutations, increased expression of other immune checkpoints such as TIM3 and CD38, lack of tumor antigens, and impaired function of effector T cells." (PMID 39227959, 2024). "We used manual gating to parse the monocytic cells into classical (CD38+CD14hi), transitional/intermediate (CD38lo/−CD14int) and non-classical (CD38−CD14−) cell types and found that the tumor-associated islands mapped to distinct viSNE coordinates." (PMID 38956268, 2024). "Baseline tumor CD38 expression and plasma EBV-DNA levels did not clearly correlate with clinical response to daratumumab." (PMID 38233570, 2024). "However, limited studies have explored resistance mechanisms to anti-CD38 MoAb in MM, with most focusing on either immune TME profiling or tumor biology using RNA/FISH-based data." (PMID 39030183, 2024). "Therefore, the presence of Tregs inhibits the activation and function of CD4+ CD38+ T cells, CD8+ T cells and M1 macrophages and consequently promotes tumor progression." (PMID 38674427, 2024). "Indeed, CD3 × CD38 × DU showed higher on-target off-tumor T cell activation and cytokine secretion compared to CD3 × DU × CD38." (PMID 39261676, 2024). "CD38 blockade either as a single agent or in combination with anti-PD-L1 did not suppress the tumor growth in the immune competent-mouse subcutaneous RPP model as compared to vehicle control or anti-PD-L1 treatment." (PMID 38533509, 2024). "Mainly, CD38 is co-expressed with PD-1 and CTLA-4 on tumor-infiltrating CD8+ TRM cells, identifying CD38 as a potential immune checkpoint marker that could be harnessed for HCC immunotherapy." (PMID 37377962, 2023). "Future studies, namely those including more recent standards of care such as anti-CD38 monoclonal antibodies, will determine the extent to which the CD27−:CD27+ T cell ratio is a useful maker of tumor specificity and response to lenalidomide-based combinations in MM." (PMID 37730678, 2023). "Cluster 2 had the highest expression and diversity of M1 and M2 macrophage markers, in particular the general macrophage marker CD68, anti-tumor markers CD169, HLA-DR, STING, and CD38, and pro-tumor markers CD163, CD204, and CD206, and immune checkpoint molecules PD-1 and PD-L1." (PMID 37620318, 2023). "However, interestingly, a positive correlation was observed with tumor multifocality and the enrichment of PD1+CD38+Tim3+ CD8+ T cells (Pearson r = 0.5933, p = 0.0011 and Spearman r = 0.5257, p = 0.0049) at the tumor site in NMIBC." (PMID 37566017, 2023). "The expression of CD38 and LMP1 in tumour tissues from 10 NKTCL patients was evaluated." (PMID 37649020, 2023). "Remarkably, among the different CD8+ T cell subsets present in the tumor tissues, the frequency of the terminally exhausted-like CD8+ T cell subset, marked as PD1+CD38+Tim3+ CD8+ T cells, was inversely correlated with a favorable outcome for patients and a responsiveness to BCG therapy." (PMID 37566017, 2023).
tumor (continued). "In addition to CD38, the epidermal growth factor receptor (EGFR) can also serve as a target for tumor cell-specific delivery of therapeutic nucleic acids." (PMID 38516300, 2023). "Interestingly, our data showed that activation markers, such as CD38&HLA-DR, were highly expressed in CD11c+CD8+ T cells in tumor tissues, as well as PD-1, compared to that of CD11c+CD8+ T cells in peripheral blood." (PMID 36798119, 2023). "While a single treatment of an anti-PD-L1 antibody showed no anti-tumor effects, sEVs loaded with CD38-targeting siRNA suppressed tumor growth and induced M1 macrophage polarization in tumor tissue of an HCC mouse model." (PMID 37762393, 2023). "It is plausible that tumour-engaged T cells rely on the ATPase activity of CD39 and NADase activity of CD38 not only to temper their activation by generating adenosine precursors but also to avoid AICD and NICD induced by sustained exposure to high concentrations of ATP and NAD+ in solid tumours." (PMID 38022596, 2023). "Considering that CD38 can cooperate with CD73 for extracellular ADO production, it would be of interest to assess the impact of host CD38 on CD73-mediated tumor cell metabolic fitness." (PMID 37261423, 2023). "To visualize that CD38 is indeed expressed by the same exhausted CD8+ T cells, we performed multiplex immunohistochemistry (mIHC) on the formalin-fixed and paraffin-embedded (FFPE) tumor tissues from the HCC patients." (PMID 37377962, 2023). "In our study, we showed that two novel [CD20×NKG2D] bibodies enhanced the ADCC of mAbs targeting CD19 or CD38 on the same tumor cells, thus, demonstrating the synergy of the NKG2D and FcγRIIIA mediated dual NK cell activation and the dual targeting of the CD20+/CD19+ or CD20+/CD38+ tumor cell lines." (PMID 37965326, 2023). "Henceforth, while we show CD38 expression in CD8+ TRM may play a role in T cell exhaustion, the other tumor-infiltrating immune cells could also contribute to the overall tumor immunity of the HCC TME." (PMID 37377962, 2023). "Replacing wild-type IFN-α with an engineered, attenuated version (att) with the capability of inducing proinflammatory markers decreased the toxicity of CD38-(att)IFN-α for animals 100-fold, without substantial loss of anti-tumor activity." (PMID 36839658, 2023). "Concerning the CD38 expression, 56.1% of the tumor slides were weakly positive or negative, whereas 43.9% showed a strong CD38 expression (Score 2+, 3+)." (PMID 37894900, 2023). "In the tumor-draining lymph node (tdLN) and bone marrow, significantly higher frequencies of CD431B11+CD4+ T cells but not CD431B11+CD8+ T cells in the PDOX treated mice were detected, and these cells differentially expressed ICOS, CD38, CD39, and KLRG1." (PMID 36796366, 2023). "In the spleens of tumor-bearing mice, we observed significantly elevated CD38+ cells in FoxP3 negative CD4+ T cells." (PMID 36757800, 2023). "This aspect requires careful evaluation in order to understand the clinical significance of CD38 in SS, although increasing evidence indicates that, regardless of the tumor cell type expressing CD38, its effect is immunosuppressive and tumor-promoting." (PMID 35251370, 2022). "Nanobody JK36AF680 specifically detected CD38-expressing tumor cells in vitro, ex vivo, and in vivo irrespective of daratumumab treatment status." (PMID 36389758, 2022). "The authors observed that the addition of DARA did not reduce bone marrow tumor burden; nevertheless, it significantly reduced CD38 expression on the surface of bone marrow AML cells." (PMID 36313735, 2022). "Seven days after tumor inoculation, mice were injected intravenously with a single dose of 5 × 106 CD38-CAR T cells or non-transduced T cells." (PMID 35765110, 2022).
tumor (continued). "Bortezomib- and dexamethasone-based regimens with or without novel anti-CD38 treatments can rapidly reduce tumor burden and improve renal function, as almost one-quarter of MM patients with severe renal impairment can even stop dialysis." (PMID 35884962, 2022). "However, the role of PARP and CD38 in the tumor immune microenvironment is more precise and related PARP inhibitors and CD38 mab have been applied in the clinic and achieved good efficacy." (PMID 35906622, 2022). "Again, tumor and blood Tregs showed the most important difference with 8% and 80% of cells that did not express any of CD38, CD40L, CD69, and GITR molecules, respectively." (PMID 36566320, 2022). "Cells in both clusters 4 and 5 also expressed CD38 and were low for TCF-1 and CD127; expression of these latter two markers on intratumoral CD8+ T cells was primarily restricted to cluster 3, a cluster shared between the tumor and circulating compartments." (PMID 35584630, 2022). "Similar to Panobinostat, Ricolinostat only enhances CD38 expression in MM and not T or NK cells, thus evading any off-target augmentation in tumor suppression by CD38 T-regulatory populations." (PMID 36139103, 2022). "All mice were bearing two subcutaneous tumors for comparative analyses of in vivo imaging signals: one CD38-positive tumor on the right shoulder and one CD38-negative control tumor on the left shoulder." (PMID 36389758, 2022). "Previous evidence in mice and humans showed that nonreversible chromatin modification is induced in non-responding patients and at late-stage tumor growth in preclinical animal models with the CD8 cells expressing CD38 and CD10150." (PMID 35110563, 2022). "Indeed, recent studies showed that, in addition to mediating ADCC in in vitro and ex vivo models, isatuximab and daratumumab directly activated NK cells and increased their lytic activity against tumor cells through CD16 and CD38 crosslinking." (PMID 35943588, 2022). "The combination of both monoclonal antibodies, however, resulted in the killing of both EGFR and CD38 expressing tumor cells, demonstrating that single-specificity CAR-T cells can be used to simultaneously target multiple tumor antigens and kill heterogeneous populations of cells." (PMID 36531912, 2022). "Vδ1 T-cells had an increased proportion of terminally differentiated effector memory (TEMRA, CD27−CD45RA+) cells, and demonstrated higher expression of the T-cell activation markers HLA-DR, CD38 and CD25 on direct ex vivo staining compared to Vγ9Vδ2 T-cells within HCC and paired tumour-free liver." (PMID 35296658, 2022). "Seven days after tumor inoculation, mice were injected intravenously with a single dose of 5 × 106 CD38-CAR T cells or non-transduced T cells as the control." (PMID 35765110, 2022). "In addition to binding CD3 on T-cells and CD38 on tumor cells, the trispecific binds CD28, which serves as both co-stimulation for T-cell activation and an additional tumor target." (PMID 35768621, 2022). "The CD27-positive, CD38-positive, and PAX5-negative tumor-induced plasmablast-like-enriched B cell (TIPB) population regulates T cell-recruiting chemokines (CCL3, CCL4, and CCL5) and increases the number of tumor-infiltrating T cells." (PMID 36361781, 2022). "The inclusion of itinerant enzymes such as CD38, CD39, and CD73 in tSV, although limited, might exert a feed-forward regulatory effect as shown for tumor-derived EV37." (PMID 35710644, 2022). "Studies have shown that CD38 can enhance adenosine (ADO) content in the tumor microenvironment to promote tumor metastasis and inhibit CD8+ T cell function while inhibiting CD38 or blocking ADO receptors can effectively improve the efficacy of targeted immune checkpoint therapy." (PMID 35906622, 2022). "Moreover, CD103+ CD38+ CD8+ T cells were blocked by PD-1 in vitro and secreted higher levels of TNF-α to mediate anti-tumor immune response." (PMID 35906622, 2022).